IL2 (interleukin 2)
Diseases named in the same sentence as IL2 in open-access papers (continued):
Sharing a sentence is not in itself a finding about the gene and the disease.
tumor (continued). "In addition, we discovered that IL-23 and PD-1 mAb had a synergistic effect in improving anti-tumor immune response, which was associated with increased levels of cytotoxic molecules such as Granzyme B and IL-2." (PMID 38902343, 2024). "This may be related to tumour-associated inflammatory response with local neutrophil infiltration and subsequent secretion of cancer-growth-promoting cytokines such as interleukin-2,-6,-10, and VEGF." (PMID 38398089, 2024). "DCs cultured in the PBMCs-IL-2 condition could promote the generation of cytotoxic T cells targeting tumor cells carrying KRAS G12D mutation." (PMID 38554155, 2024). "Under the IL-2-deficient conditions of tumor microenvironment (TME), our MBP IL-2-expressing NK-92 (MBP NK) cells indeed showed improved proliferation and higher antitumor activity against a hematological tumor model and a solid tumor spheroid model compared to the parental NK-92 cells." (PMID 37056568, 2023). "Engineered interleukin-2 (IL-2) variants yield better electrostatic complementarity to the IL-2 receptor beta chain and faster association kinetics leading to in vivo enhancement of immune effector responses and anti-tumor effects." (PMID 37558752, 2023). "Furthermore, IL-2 and IL-2R have been implicated in the metastatic process, whereby cancer cells migrate from the primary tumor to distant body parts." (PMID 37516849, 2023). "TG4001 (Transgene, Illkirch-Graffenstaden, France) (also known as tipapkinogene sovacivec) is a non-propagative, highly attenuated vaccinia vector (MVA) which is engineered to express the coding sequences of the HPV16 E6 and E7 tumor-associated antigens and the cytokine, IL-2." (PMID 36992219, 2023). "Additionally, IL-2 is avoided in GML therapy due to the toxicities associated with higher doses needed to maintain the anti-tumor function of transferred T cells." (PMID 38090585, 2023). "Remarkably, a heterotypic spheroid model composed of tumor cells, fibroblasts, and immune cells was developed to assess the efficacy of novel cancer immunotherapy agents [i.e., IL-2 variant and tumor- or fibroblast-targeted T cell bispecific antibody] both as monotherapy and in combination." (PMID 37114038, 2023). "Previous experiments in our lab have shown that TPV recombinants, including one that expresses mouse IL-2 with the viral thymidine kinase gene (66R) deleted, were effective at inducing significant tumor regression in an outbred immune-deficient nude mouse model." (PMID 37628585, 2023). "In addition, IL-2 can cause complete and long-lasting tumor regression in patients with metastatic melanoma and renal cancer." (PMID 36532066, 2022). "Notably, tumor responses were detected in 50% rGBM patients receiving the combined therapy of IL-2-encoding genes and herpes simplex virus type 1 thymidine kinase (HSV-TK) genes." (PMID 35135556, 2022). "Tumor-associated macrophages (TAMs) can secrete IL-2, IFN, and IL-12 to kill tumor cells, but they can also secrete a variety of angiogenic factors and cytokines to promote the growth of tumor cells and IL-10 to inhibit the antitumor response of cytotoxic T cells." (PMID 36230816, 2022). "Th1 cytokines, such as IL‐1β, IL‐2, IL‐12, IL‐18, TNFα, and IFNγ, are associated with proinflammation, while Th2 cytokines, such as IL‐4, IL‐5, and TGFβ, play a suppressive role in the tumour immune microenvironment." (PMID 35430766, 2022). "NKp46 has been associated with good prognosis in human NSCLC (owing to the formation or maintenance of tertiary lymphoid structures (TLS), release of IL-22, TNF-α, IL-8, and IL-2 and recognition of lung tumour cells and tumour-associated fibroblasts via the NKp44 receptor." (PMID 35406451, 2022). "IL-2 has a dual role in regulating tumor-associated immunity." (PMID 36119037, 2022).
tumor (continued). "Several strategies have been developed to overcome the harmful side effects of IL-2-based therapy and to achieve better anti-tumor efficacy, e.g., introducing mutations into IL-2 fusion proteins affecting IL-2R subunit binding, and/or targeting IL-2 to tumor cells." (PMID 35874707, 2022). "We have previously shown that ICE®/tumor-antigen associated cross-link-experienced healthy donor-derived NK cells are triggered to phenotypic changes boosting proliferation and cytotoxic capacity in response cytokines, such as IL-2 and IL-15." (PMID 35225870, 2022). "Therefore, we focused on the tumor-infiltrating Pmel-1 to identify the factor associated with the reduced additive effect in the TBI/IL-2 combination." (PMID 36497152, 2022). "Reports of spontaneous regression, particularly following nephrectomy, the demonstration of tumour-associated antigens and tumour-specific T-cells and tumour-associated immunosuppression led to initial immunotherapy treatments with cytokines such as IL-2." (PMID 34885149, 2021). "In comparison to IL-2, T cell clones generated in the presence of IL-15 displayed higher proliferative capability and cytokine secretion potential and were effective in causing tumor regression upon transfer in mice." (PMID 33671252, 2021). "Thus, in order to activate T cell antitumor activity, DCs can be modified with tumor-associated antigen(s), fused with tumor cells, or can be armed in cytokine adjuvants, such as IL-2." (PMID 34885122, 2021). "However, recombinant IL2-based therapy is associated with high systemic toxicity and activation of regulatory T-cells, which are associated with the pro-tumor immune response." (PMID 33579033, 2021). "After being secreted by activated T cells, monocytes, and/or tumor-associated stromal cells, IL-3 could induce a concomitant increase in the percentage of both Foxp3+ Tregs and IL-2 secreting Th cells in a dose-dependent manner." (PMID 33868318, 2021). "The eight-gene-signature prognostic model (ANGPTL5, CD1B, CD1E, CNTFR, CTSG, EDN3, IL12B, and IL2)-based high- and low-risk groups were significantly related to overall survival (OS), tumor microenvironment (TME) immune cells, and clinical characteristics in LUAD." (PMID 34745015, 2021). "The interaction of LAG3 and FGL1 may cause changes in the tumor immune microenvironment, such as the reduction of IL-2 levels." (PMID 35111155, 2021). "These NK cell-deficient mice were unable to control tumor growth and had a median survival rate of 21.5 days, while mice treated with donor IL-2 NK cells were more resistant to tumor growth and survived longer with half of the mice still alive 70 days after tumor injection." (PMID 34071607, 2021). "Interestingly, IL-2 treatment of WASp-deficient NK cells rescues the defective killing capacity, and IL-2 naturally produced by tumor cells increases the killing capacity by WASp-deficient NK cells." (PMID 33621210, 2021). "Not all studies prefer the promotional effect of exosome in immune escape, in some cases, gene-modified tumor cells can cause the TDEs contain glycosyl-phosphatidylinositol-anchored interleukin 2 (GPI-IL-2), resulting in increased antitumor effects and hamper immune escape." (PMID 33430032, 2021). "However, systemic administration of high doses of IL2 can be toxic, causing capillary leakage syndrome and stimulating pro-tumor immune response." (PMID 32560387, 2020). "In a recent study intravaginal immunization with pcDNA-3CRT/E7 co-administrated with DNA encoding IL-2 followed by electroporation in tumor-bearing mice, a stronger anti-tumor CTL response and enhanced antitumor effects were induced compared to mice treated with the vaccine alone." (PMID 32455616, 2020). "Therefore, we cultured ex vivo isolated tumor cells with autologous TIL, which comprises tumor-associated cells, in IL-2 medium, and stimulated the culture with zoledronic acid or medium." (PMID 32695112, 2020).
tumor (continued). "Additionally, MCPyV TAg-specific cells gated on CD3+CD4+TNFα+ cells were polyfunctional for IL-2 and the Th1 effector molecules granzyme B, IFNγ, and TNFα, a feature associated with immune-mediated tumor clearance." (PMID 33362774, 2020). "Interleukin-2 can induce an anti-tumour response, but is associated with toxicity." (PMID 32005826, 2020). "However, the vascular leak syndrome associated with the high-dose IL-2 treatment regimen has limited its use in tumor immunotherapy." (PMID 31114758, 2019). "Similarly, adenoviral delivery of XCL1 and tumor-associated antigens to DC increases IL-2 and IFNγ production by NK and T cell populations." (PMID 30979057, 2019). "It appears that the IL-2-dependent pathway (the pathway involving the cytokine and the corresponding receptor) does not serve as the key mechanism underlying the autocrine activation of T cell proliferation and the in vitro survival of the tumor clone." (PMID 29495627, 2018). "Recently, it has been described as a novel class of monomeric tumor-targeted immunocytokines in which a single engineered IL-2 variant (IL-2v) with abolished CD25 binding is fused to the C-terminus of an antibody against the CEA or fibroblast activation protein-α (FAP)." (PMID 30619269, 2018). "When anti-IL-2 blocking antibody was added to conditioned media from Tmem, this effect was lost, suggesting that paracrine release of IL-2 from Tmem may potentiate tumor cell death caused by Teff." (PMID 29843822, 2018). "However, along with induction of potent anti-tumor T cells, IL-2 is also known to cause Activation Induced Cell Death (AICD) and differentiation into immunosuppressive regulatory T cells." (PMID 30713539, 2018). "However, these modified IL2 fusion proteins display slower plasma clearance than naïve IL2 and can cause significant activation of T cells outside the tumor and consequently they can still cause toxicity." (PMID 29467958, 2018). "Reduction of several layers of suppression in young tumor-associated CD4+ T cells may help account for the improved tumor response seen in young mice to IL-2/CD40 treatment." (PMID 30560130, 2018). "Moreover, IFNγ and IL-2 production in response to tumor recognition were reduced when Y206 and Y209 were mutated with either of both alanine or glutamic-acid residues." (PMID 30400835, 2018). "Macrophages associated with the tumor have opposite roles in the malign environment: they can kill the cancerous cells after being activated by IL-2, interferon, and IL-12, but also they can secrete angiogenic and lymphangiogenic growth factors that enable the tumor cells to proliferate." (PMID 30417020, 2018). "Importantly, 6 days after transfer into tumor-free T/B/NK cell-deficient NSG mice (supplemented daily with IL-2), IL-12/15/18 pre-activated NK cells were superior in IFN-γ production when restimulated ex vivo with K562 cells or cytokines." (PMID 30546366, 2018). "One of the pioneering work was published more than 20 years ago by Quintin-Colonna and collaborators, describing the efficacy of repeated local injections of human IL-2-genetically engineered xenogeneic cells at the primary tumor site after its surgical removal in association to radiotherapy." (PMID 29534457, 2018). "irAEs following IL-2 therapy are associated with improved tumor control and overall survival." (PMID 29254506, 2017). "Drug targeting, efficient stimulation of immune cell infiltration, and specific elimination of tumor or fibroblast spheroid areas were demonstrated following treatment with a novel immunocytokine (interleukin-2 variant; IgG-IL2v) and tumor- or fibroblast-targeted T cell bispecific antibody (TCB)." (PMID 27858101, 2017). "Therefore, Tregs restrict the availability of IL-2 for NK cells causing suppression of NK cell expansion and activity, thus validating the effect of Treg depletion to enhance tumor suppression by NK cells." (PMID 26802025, 2016).
tumor (continued). "In addition, IL-2 receptors (IL-2R) were shown to be present on human neutrophils, and that IL-2-neutrophil interactions are believed to be important in both tumour rejection and increased susceptibility to bacterial infections." (PMID 27434108, 2016). "In multicenter phase I/II clinical trial, high-risk tumor patients were treated either with freshly isolated or IL-2-stimulated NK-donor lymphocyte infusion (NK-DLI) after haploidentical SCT without any signs of GvHD when less than 25 × 103/kg NK cells were injected." (PMID 27891129, 2016). "Besides, a long-term anti-tumor protection against recurrence and challenge was conferred in mice by granulocyte-macrophage colony-stimulating factor or IL2 gene electrotransfer, in association with ECT treatment of B16 tumors." (PMID 26993326, 2016). "In conclusion, intratumoral administration of IFN-α2, IFN-γ and IL-2 can lead to immune sensitization of the established tumor, whereas GM-CSF may contribute to tumor-associated immunosuppression." (PMID 26107883, 2015). "We determined whether activation preferentially affects known NK cell subsets, and whether a tumor-induced activation of murine NK cells also causes phenotypical changes either before or after culture in IL-2." (PMID 25101668, 2014). "Additionally, it is well-known that NK activity, which mediates IL-2 anti-tumor activity, is suppressed during conditions of AA deficiency." (PMID 24884532, 2014). "We determined a clear antitumor effect of IL-12 plasmid DNA against an experimental murine tumor, which was associated with shift to a Th1-type cytokines profile, with expression of IL-2, IL-12 and IFN-γ cytokines and reduced expression of IL-10, IL-4 and TGF-β1 cytokines." (PMID 24808638, 2014). "However, after the tumor was treated with three intratumoral injections of plasmid containing IL-12 cDNA, it showed a cytokine profile associated with Th1 with expression of IL-2, IL-12, and IFN-γ cytokines and reduced expression of IL-10, IL-4, and TGF-β1." (PMID 24808638, 2014). "Incontrast, while NK cells that had been rested in complete medium in the absenceof IL-2 displayed very little cytotoxicity against the MHC class I deficientK562 tumour cell line, addition of IL-2 alone enhanced NK cell cytotoxicitysubstantially from 24h up to 48h of culture." (PMID 23874793, 2013). "Our study showed that levels of both INF-γ and IL-2 in mice treated with recombinant GM-CSF, IL-21 and Rae-1 gene expression vectors were highly expressed and negatively associated with the tumor volumes seen in tumor-bearing mice." (PMID 24350772, 2013). "Moreover, prophylactic vaccination with 102 pfu of IL-2 or IL-15 encoding vectors reduced the tumor burden, whereas the same dose of Flt3L vector completely prevented tumor growth." (PMID 24312302, 2013). "Thus, our data suggest the additional administration of the DNA construct encoding NKG2D-Fc-IL2 is able to enhance the therapeutic anti-tumor effect first generated by the gene gun-administered CRT-E7 DNA vaccine." (PMID 22509395, 2012). "Administration of cytokines such as IL-2 to the tumour environment may stimulate the immune system to discern and assail the solid tumour cells; however caution must be taken as high systemic levels of IL-2 cause toxicity." (PMID 22737166, 2012). "In a mouse model of renal cancer, the efficacy of IL-2/anti-CD40 agonist antibody was associated with conversion of the immunosuppressive tumor milieu to an immunogenic milieu which was rich of inflammatory chemokines including CXCL-9, CXCL-10, CCL-5, and CCL-3." (PMID 22778760, 2012). "Furthermore, we showed that TC-1 tumor-bearing mice intramuscularly injected with DNA encoding NKG2D-Fc-IL2, followed by electroporation, exhibited an increased number of luciferase-expressing E7-specific CD8+ T cells at the tumor location." (PMID 22509395, 2012). "Also, expanded TIL secreted higher amounts of Th1 cytokines, IFN-γ and IL-2, which are associated with anti-tumor immunity." (PMID 22279573, 2012).
tumor (continued). "We further determined that the TC-1 tumor-bearing mice treated with the DNA construct encoding NKG2D-Fc-IL2 could exhibit enhanced proliferation of the luciferase-expressing E7-specific CD8+ T cells at the tumor loci." (PMID 22509395, 2012). "As CD8+ T cells generally lose the ability to produce IL-2 upon differentiation, the failure of cytokines to enhance IL-2 production suggests that most tumor-associated T cells may be terminally differentiated effectors." (PMID 21203522, 2010). "Interleukin-2 could also activate MCs, and induce tumour rejection, inhibiting tumour-associated vascularity." (PMID 19935800, 2009). "The tumour regression seen on administration of IL-2 may be associated with concomitant activation of tumour-specific T cells." (PMID 19384299, 2009). "Despite its promise, effective responses to adoptive immunotherapy have been documented against only a restricted number of tumor types and this approach to cancer therapy has been further restricted by toxicity associated with the need for exogenous administration of interleukin-2." (PMID 16507098, 2006). "Therefore, Tregs mainly downregulate the quantity and activity of Teffs by secreting different soluble negative immune molecules and suppress the growth of Teffs and NKs by competing with and depleting IL-2, which can cause immune escape of tumor cells and induce drug resistance in AML." (PMID 40008144, 2025). "The emergence of targeted IL-2 delivery strategies, including immunotoxins, immunocytokines, and engineered variants, has helped mitigate these issues by improving specificity to the tumor microenvironment, reducing off-target effects, and enhancing therapeutic outcomes." (PMID 39852848, 2025). "Besides, FGF/FGFR promoted the survival of Treg cells and the M2 polarization of tumor‐associated macrophages (TAMs) by facilitating interleukin‐2 (IL‐2)‐mediated signal transducer and activator of transcription (STAT5) phosphorylation, thereby promoting an suppressive immune microenvironment." (PMID 40859961, 2025). "Therefore, we hypothesize that the employment of IL-2F fusion protein encoding cRNA (cRNAIL-2F) for in situ production of IL-2F at the tumor site may overcome the limitations associated with conventional IL-2 therapy." (PMID 40009662, 2025). "Similarly, in tumor models, tumor‐associated neutrophils upregulate GZB when stimulated with a cytokine mix (IL‐2, IL‐12, IL‐21) alone or combined with a TLR4 agonist, demonstrating that innate (TLR) and adaptive (cytokine) signals converge to trigger neutrophil GZB production." (PMID 41244336, 2025). "However, high-dose IL-2 therapy may also stimulate regulatory T cells, thereby suppressing immune responses against tumor-associated antigens." (PMID 40647561, 2025). "This dual approach enables tumor-specific targeting, while avoiding the induction of systemic inflammation caused by cytokines, such as cytokine release syndrome and vascular leakage, through the off-target effects of IL-2 on peripheral effector and endothelial cells." (PMID 38834889, 2024). "Moreover, IVT-mRNA may encode cytokines that are considered to modulate the tumor microenvironment (IFNα2b, IL-2 and IL-12), inducing a broad immunity against cancer cells." (PMID 37998753, 2023). "When exposed to the tumor microenvironment for a long time, the balance is broken and the inhibition signal is enhanced, leading to T cell depletion, and loss of proliferation, secretion of cytokines (including IL-2, TNF, and IFNγ), and degranulation by T cells." (PMID 35770416, 2023). "Thus, the Ce6-PDT-associated decrease in PD-1/PD-L1 interaction is linked with increased tumor cells death in distant tumors with the enhanced frequency of CD8+ T cells through the release of IL-2, suppression of CD39+ T cell activity, and increased Granzyme B levels." (PMID 36944686, 2023).